TNF (tumor necrosis factor)
Diseases named in the same sentence as TNF in open-access papers (continued):
Sharing a sentence is not in itself a finding about the gene and the disease.
viral infection (continued). "It was quite unexpected that many proinflammatory cytokines/chemokines, such as TNF-α and IL-6, were not significantly higher during acute ZIKV infection in an endemic area, in contrast with other viral infections, such as dengue." (PMID 29774022, 2018). "Our present work reveals that upon the IAV infection, human macrophages produced significantly higher levels of pro‐inflammatory cytokines, such as TNF‐α, IFN‐α, and IL‐6, compared to that with no virus infection." (PMID 28646616, 2017). "In NHP MDM the response to 17D virus infection was similar to what was seen in human MDM with evident increases in IFNα2 and TNFα, but little evidence of a pro-inflammatory response." (PMID 27191161, 2016). "Remarkably and in sharp contrast with pNK cell response to viral infection, there were no changes in secretion levels of cytokines such IL-12, IL15, type I IFN, TNFα or IFN-γ that are all known to regulate NK cell function." (PMID 23592985, 2013). "For neonatally rats, it was assumed that the lack of weight gain was due to the virus infection itself but in experimental LCMV-infection of mice, weight gain correlated with CD4+ T-cell activation rather than with TNF expression." (PMID 22848506, 2012). "The only protein identified in the TNF alpha hub that was down-regulated, namely PTPN12, is also the only protein that has not yet been reported in any other viral infections to date." (PMID 23240068, 2012). "Further analysis also showed that while the production of IL-6 and IL-10 are dependent on viral replication, production of TNF-α also occurs after exposure to UV-inactivated TCRV particles and is thus independent of productive virus infection." (PMID 21572983, 2011). "Although IRF3 has been shown to mediate TNF induction under various circumstances, such as lipopolysaccharide stimulation or certain viral infections, the collaboration between IRF3 and IRF7 resulting in sustained TNF induction has not been recognized before." (PMID 18617992, 2008). "Notably, in the absence of viral infection, γ-PGA alone generally does not elevate systemic TNF-α levels in murine serum." (PMID 41155933, 2025). "While our results indicate that TNFα induces HK2 expression, which we found to be important for TNFα-induced glycolytic activation, its deletion did not impact the TNFα-mediated induction of the UDP-glucose pool, nor did it restore viral infection in the face of TNFα treatment." (PMID 35834576, 2022). "Although the TGFβ2 factor, recently recognized as a key factor in fibrosis induction, did not result upregulated by virus infection in HUVECs, other factors belonging to TGFβ superfamily were promoted in particular by HHV-6A, including GREM1 and INHBE, IL-4, IL-5, TNF, and MMP9." (PMID 31878218, 2019). "In contrast, the expression of Cre in WT MEF cells did not affect the expression level of TAK1 or RIPK1 S321 phosphorylation in response to TNFα, suggesting the blocked RIPK1 S321 phosphorylation in TAK1F/F Cre MEFs was not a result of virus infection or Cre expression per se." (PMID 28842570, 2017). "Our findings demonstrate that activation of Fas modulates poly I:C-induced cytokine production in both a positive (IP-10) and a negative (TNFα, IL-8, IFN-β, IL-10) manner implicating a role for Fas ligation in tailoring the immune response following viral infection." (PMID 25849666, 2015). "The cytokines IL-6, IL-10, IL-12, IL-17, TNF-α and IFN-γ were evaluated in the Cerebrospinal fluid (CSF) of patients with meningoencephalitis with and without viral infections as well as in control CSF samples using the cytometric bead array (CBA – BD biosciences)." (PMID 26286516, 2015). "First, a synergistic production of TNF-α, IFN-γ or IL-12 was observed when MoDCs were stimulated with heat killed pneumococcus at 6 hr, but not 0 hr nor 24 hr after virus infection." (PMID 21771345, 2011).
viral infection (continued). "Thus, MYXV is non-permissive in primary human macrophages because the virus infection co-induces both IFN and TNF, that rapidly renders cells in the culture (including even admixed “permissive” human fibroblasts) non-permissive for the virus in a paracrine fashion." (PMID 28157174, 2017). "Higher MxA levels in patients with viral infection compared with patients with bacterial infection can be explained by the fact that MxA protein is induced exclusively by type 1 IFN and not by IFN-gamma, IL-1, TNF-alpha, or any of the other cytokines induced by bacterial infection." (PMID 26672961, 2015).
Crohn disease (1,176 papers, 2005 to 2026). A gastrointestinal disorder characterized by chronic inflammation involving all layers of the intestinal wall, noncaseating granulomas affecting the intestinal wall and regional lymph nodes, and transmural fibrosis. "This is evident in Crohn's disease and some cases of UC, where IL‐17/IL‐22 and TNF form an inflammatory axis causing deep crypt damage and erosions." (PMID 40679787, 2025). "The combined assault of IFN‐γ and TNF causes focal epithelial loss and loosened TJs, as seen in Crohn's disease, in which Th1 cytokines drive mucosal ulceration." (PMID 40679787, 2025). "Many publications demonstrate that growth retardation in Crohn’s disease patients is associated with poor prognosis and is an indication for anti-TNF treatment." (PMID 41597331, 2025). "Another case report presented a case of AIED in a patient with Crohn's disease that showed improvement to anti‐TNFα therapy, halting the progression of hearing loss, as well as improving hearing by an average of 15 dB across all frequencies." (PMID 39959556, 2025). "Single-cell analysis of inflammatory tissues from patients with Crohn's disease has revealed a unique cellular module associated with the ineffectiveness of TNF inhibitors." (PMID 38143258, 2024). "It was stated that loss of intestinal barrier function mediated by TNF signaling was highly relevant to the inflammatory pathophysiology observed in Crohn’s disease and celiac disease." (PMID 39619663, 2024). "Crude odds ratio and risk ratio of early anti-TNF therapy for 1-year outcomes in pediatric Crohn’s disease patients." (PMID 38011797, 2024). "The association between TNF‐α‐857 polymorphism and ulcerative colitis and Crohn's disease has been investigated, and a significant relationship with Crohn's disease was observed." (PMID 38572118, 2024). "This study provides evidence to support the use of early anti-TNF therapy in paediatric patients with newly diagnosed Crohn’s disease, in particular in presumed high-risk patients, ie, those with moderate-to severe disease activity or the presence of any POPO." (PMID 38011797, 2024). "Treatment guidelines for paediatric Crohn’s disease [CD] suggest early use of anti-tumour necrosis factor alpha [anti-TNFα] in high-risk individuals." (PMID 38011797, 2024). "Elevated levels of TNF in Crohn’s disease tissue samples or treatment of colon cell lines with exogenous TNF are associated with decreased abundance and thickness of the mucus barrier, suggestive of a role for TNF in maintaining intestinal mucus." (PMID 37643009, 2023). "In previous studies, TNF-α overexpression in mice had been shown to result in the development of IBD pathologies like Crohn’s disease (CD), giving evidence for TNF-α as one of the causative factors in IBD pathogenesis." (PMID 38137946, 2023). "Two unrelated adult patients presented with gastrointestinal manifestations, one with Crohn’s disease-like ileo-colic inflammation refractory to anti-TNF and the other with lymphocytic leiomyositis causing severe chronic intestinal pseudo-occlusion." (PMID 37156989, 2023). "The expansion of apoptosis-resistant intestinal TNFR2+IL23R+ T cells is associated with resistance to anti-TNF therapy in Crohn’s disease (CD)." (PMID 38137450, 2023). "For instance, serum S100A12 levels have been associated with response to anti-TNF therapy in patients with juvenile idiopathic arthritis and Crohn’s disease." (PMID 36555597, 2022). "IL-12 is a pro-inflammatory cytokine that is involved in the expression of TNF-α and is known to be associated with Crohn's disease." (PMID 36039384, 2022). "In the treatment of RA, anti-TNF therapy was found to increase the risk of cancer and severe infections, while anti-TNF therapy for Crohn’s disease has been reported to be correlated with a significantly higher risk of lymphoma." (PMID 36678712, 2022).
Crohn disease (continued). "Studies on relations between polymorphism in TLR gene and the clinical response of anti-TNF α, in psoriatic, Crohn’s disease, and ulcerative colitis patients showsative." (PMID 35370680, 2022). "This case report highlights the potential rare association between GBM and anti-TNF therapy and further discusses the difficulty of managing active Crohn's disease with concomitant GBM, specifically the difficulty encountered in managing a disease flare." (PMID 35719803, 2022). "In their study apoptosis-resistant intestinal TNFR2 + IL23R+ T cells were associated with resistance to anti-TNF therapy in Crohn’s disease." (PMID 36384462, 2022). "Female, younger age, smoker, ileocolonic Crohn's disease, and the types of anti-TNF were significantly associated with such risk." (PMID 35300336, 2022). "Stricturing Crohn’s disease is a challenging problem to manage and anti TNF therapy is associated with good short-term treatment success and a modest long-term response." (PMID 34083575, 2021). "The patient’s underlying Crohn’s disease was in clinical and endoscopic remission under therapy with the anti-TNF antibody infliximab, which had been started 11 months ago." (PMID 34616488, 2021). "TNFα has been shown to induce barrier loss in epithelial cells during Crohn’s disease in vitro and in mice." (PMID 34740333, 2021). "IBD-included ulcerative colitis (UC) and ‘ ‘Crohn’s disease (CD) are characterized by the release of pro-inflammatory cytokines, for example, TNF-α (alpha tumor necrosis factor), causing further damage to the barrier function and perpetuating inflammation." (PMID 33809584, 2021). "The magnitude of the risk reduction was highest in men with Crohn’s disease exposed to anti-TNF agents (HR 0.54, 95% CI 0.40–0.72)." (PMID 34453143, 2021). "It has been demonstrated that TNFα is an early potent proinflammatory cytokine in the inflammatory process underlying Crohn’s disease." (PMID 34681815, 2021). "Enteral nutrition (EN) is effective in Crohn’s disease (CD) patients and has been shown to have an inhibitory effect on loss of response to anti-tumor necrosis factor (TNF)-alpha antibody therapy; however, the current level of evidence is not sufficient." (PMID 31641874, 2020). "Increased Paneth cell death has been identified in the ileum of Crohn’s disease patients, and treatment of control patient biopsies with TNF has been shown to reduce Paneth cell-associated lysozyme mRNA, which can be rescued by Nec-1, a RIP1 inhibitor." (PMID 32671059, 2020). "Anti-TNF drugs are a fundamental part of the treatment of Crohn’s disease(CD), so identifying factors related to loss of response is of greatimportance in clinical practice." (PMID 33237166, 2020). "Antibody neutralization studies implicated a significant role for TNF in the pathogenesis of Crohn’s disease." (PMID 30065229, 2018). "This research is directly answering one of the research recommendations from NICE to investigate clinical outcomes associated with using the ELISA kits for TDM in people with Crohn disease who respond to treatment with TNF alpha inhibitors." (PMID 30341052, 2018). "The onset of B-cell lineage lymphomas and hepatosplenic T cell lymphoma (HSTCL) has been observed in patients with Crohn’s disease who received anti-TNF-α agents mainly in association to thiopurines." (PMID 28222785, 2017). "No safety issues or increased risk of infection were reported when anti-TNF vaccination was administered in humans (Crohn’s disease: NCT00808262; RA: NCT01040715)." (PMID 29184553, 2017). "There are several studies that have investigated the association of TNFα SNPs with different diseases such as colorectal cancer, pre-eclampsia, prostate cancer and Crohn’s disease." (PMID 28670429, 2017). "The interaction between protein Tumor Necrosis Factor (TNF) and its receptors is implicated in several physiological functions and diseases, such as rheumatoid and psoriatic arthritis, Crohn’s disease, and multiple sclerosis." (PMID 28426652, 2017).
Crohn disease (continued). "The correct assembly of tight junction components is critical to preserve barrier integrity and TNFα is recognised as one of the main mediators associated with inflammation in Crohn's disease and CD." (PMID 24915573, 2014). "We report a rare case of steroid resistant Crohn's disease associated with multivisceral sarcoidosis, treated successfully by an anti-TNFα agent, infliximab." (PMID 24653848, 2014). "There are a few reports that described the risk of severe hepatitis in patients with Crohn's disease treated with anti-TNF-α agents; however, information was still insufficient." (PMID 25374717, 2013). "Up to now, several studies of the -1031(T/C) polymorphism of TNF-α were reported including Behcet's disease, large joint arthropathy, and Crohn's disease." (PMID 21970639, 2011). "Because the children with the most severe cases of either JIA or Crohn's disease are also the children most likely to be treated with anti-TNF therapy, it is difficult to make a determination of causality." (PMID 20546618, 2010). "Other TNF inhibitors are approved for use in this population, however, and malignancies associated with TNF inhibitor use in pediatric patients with Crohn's disease have been reported." (PMID 20546618, 2010). "In the presented case, the patient's treatment with anti-TNF-alpha agents for Crohn's disease could indeed represent a significant predisposing factor for the development of OSCC." (PMID 39963098, 2025). "For instance, the STORI trial—a multicenter prospective study assessing relapse risk after withdrawing maintenance anti-TNF in Crohn’s disease (excluding perianal disease)—found relapse rates of 43.9% at 12 months and 52.2% at 24 months, with a median time to relapse of 16.4 months." (PMID 40868182, 2025). "Moreover, the Sp140 mutations predicted the responsiveness of Crohn’s disease patients to anti-TNF therapy, suggesting its role in regulating TNF response." (PMID 41037321, 2025). "Perhaps even for other pathologies such as Crohn’s disease where TNF-α also causes apoptosis." (PMID 40170863, 2025). "One study showed that expression of the cytokine oncostatin M is increased in inflamed sites of the mucosa of patients with Crohn’s disease and ulcerative colitis; it also revealed that a high level of oncostatin M expression prior to treatment is associated with the failure of anti-TNF therapy." (PMID 39327633, 2024). "Whether immunomodulators or biological treatments (anti-TNFα therapy) increase the risk of post-operative complications in Crohn’s disease patients is still a matter of debate." (PMID 38792351, 2024). "The hallmark of Crohn’s disease is chronic inflammation, which is caused and sustained by hyperactivated effector immune cells that increase the production of proinflammatory cytokines, specifically tumour necrosis factor alpha (TNF-α)." (PMID 39456510, 2024). "Previous studies have demonstrated associations between TNF-α − 1031T/C polymorphism with different oral malignancies and autoimmune or inflammatory diseases such as Behçet’s disease, periodontitis, Crohn’s disease, chronic obstructive pulmonary disease, Gastric Carcinoma." (PMID 38317095, 2024). "Like TNFα, IL-6 is upregulated in Crohn’s disease (CD) especially in patients associated with Mycobacterium avium paratuberculosis (MAP) infection, and both cytokines have been targeted as a therapeutic option for the treatment of the disease despite the accepted partial response in some patients." (PMID 39170608, 2024). "Both diseases have been shown to respond to TNF-α antibodies (including infliximab and Adalizumab) involving inflammatory pathways involving IL-23 and Th-17 that have been linked to hidradenitis suppurativa and Crohn’s disease." (PMID 39926114, 2024). "Interestingly, Ruminococcus gnavus is associated with Crohn’s disease, likely through the ability of R. gnavus to synthesize and secrete glucorhamnan polysaccharides, which can lead to TNFα secretion by dendritic cells." (PMID 37190186, 2023).